CD44 (CD44 molecule (IN blood group))
Diseases named in the same sentence as CD44 in open-access papers (continued):
Sharing a sentence is not in itself a finding about the gene and the disease.
liver cancer (113 papers, 2011 to 2026). An epithelial or non-epithelial malignant neoplasm that arises from the liver. "Together, these observations implicate age-associated expression of hepatocyte CD44, known for its role in liver cancer initiation, in activation of the immune suppressive IL6/JAK/STAT3 pathway and T cell dysfunction in the aged liver." (PMID 41509421, 2025). "In HCV-induced HCC, Variant 9 of CD44 was identified as a biomarker of liver cancer stem cells, and its expression correlated with tumor invasiveness and poor patient survival." (PMID 34065048, 2021). "This study aims to determine prognostic and diagnostic efficacies of TIPRL/LC3/CD133/CD44 for early liver cancer." (PMID 34208132, 2021). "This study assessed the human TOR signaling regulator (TIPRL)/microtubule-associated light chain 3 (LC3)/prominin-1 (CD133)/cluster of differentiation 44 (CD44) as potential diagnostic and prognostic biomarkers for early liver cancer." (PMID 34208132, 2021). "Various CD44 splice variants are associated with tumor progression in epithelial‐type carcinomas including liver cancer." (PMID 31294922, 2019). "CD44 is a receptor of hyaluronate involved in cell-cell adhesion and migration and it has been associated with tumor cell invasion and migration in liver cancer." (PMID 26097877, 2015). "A CD44 variant was reported to influence the redox status to protect CSCs from oxidative stress in liver cancer." (PMID 26540347, 2015). "E-cadherin knockout mice will develop spontaneous liver cancer and the loss will promote chemical induced (with diethylnitrosamine) liver cancer with strong expression of stem cell marker CD44 and EMT marker vimentin." (PMID 25197668, 2014). "However, the mechanisms underlying CD44’s function in liver diseases other than liver cancer are still poorly understood." (PMID 38731968, 2024). "CD44 is clearly associated with liver cancer initiation, poor prognosis, and cancer cells stemness." (PMID 38783892, 2024). "Furthermore, our study provides evidence for the significant prognostic and diagnostic efficiencies of TIPRL/LC3/CD133/CD44, either individually or in conjunction, to detect early liver cancer." (PMID 34208132, 2021). "This down-regulation may be caused by down-regulation of SPP1 which was shown to increase the synthesis of the CD44 variant CD44v6 in liver cancer cells." (PMID 31882946, 2019). "It has been reported that FoxM1 can increase CD44 expression via binding with CD44 promoter in human liver cancer cells." (PMID 40050970, 2025). "Elevated cholesterol levels promote the translocation of CD44 to lipid rafts, inhibiting the progression of liver cancer." (PMID 40443776, 2025). "This novel formulation integrates the structural stability of sterosomes with HA-mediated CD44 targeting and pH-responsive release, offering a unique and effective nanoplatform for liver cancer therapy." (PMID 40862923, 2025). "Single-cell sequencing and ligand-receptor relationship analysis in liver cancer have shown significant interactions between HA secreted by myCAFs and tumor receptors such as CD44 and HMMR." (PMID 40813707, 2025). "In sum, CD44 has many reported functions that can potentially contribute to its role in liver cancer initiation." (PMID 41509421, 2025). "Csn6LKO mice also showed less tumors, smaller tumor size, smaller ratios of liver/body weight and decreased liver cancer markers expression, such as CD44 and ALDHA, when compared with Csn6fl/fl mice." (PMID 38308184, 2024). "CD44 facilitates transendothelial migration of liver cancer cells by promoting expression of integrin subunit beta 2 (Itgb2)." (PMID 37174657, 2023).
liver cancer (continued). "CD44’s significant correlation with HCC aggressiveness was also evaluated in another study that utilized formalin-fixed tissue sections from 107 resected liver cancers to detect the expression of various isoforms of CD44." (PMID 35200757, 2022). "This difference in CD44 expression levels was also confirmed at the protein level by analyzing the expression of this receptor on the plasma membranes of liver cancer cells." (PMID 35164326, 2022). "We further analyzed the expression of CSC surface markers CD133 and CD44 in liver cancer cells by modulating Dicer expression." (PMID 35253323, 2022). "The occurrence and development of liver cancer is regulated by the immune system, and a lot of important immune molecules, CD44, IL-6, CLCX8." (PMID 35602902, 2022). "In conclusion, our findings suggest that during SD in the internal environment, exosome CTLA-4 regulates the PTEN/CD44 signal pathway to promote the proliferation, self-renewal, and metastasis of liver cancer." (PMID 34744733, 2021). "Further data indicate that HCV replication was particularly enhanced in liver cancer stem cells expressing CD44 and epithelial cell adhesion molecules (EpCAMs) and that osteopontin also activated HCV replication in these cells." (PMID 34065048, 2021). "These important findings suggest that the internal environment of SD exosome CTLA-4 promotes the metastasis of liver cancer by regulating the PTEN/CD44 pathway." (PMID 34744733, 2021). "For example, CD44 sponges miR-105-5p to regulate PES1 in liver cancer stem cells to push tumor growth." (PMID 34592939, 2021). "In summary, the variables TIPRL, LC3, CD133, and CD44 reflect the overall survival of liver cancer patients." (PMID 34208132, 2021). "We detected reduced expression levels of EPCAM, CD13, CD133, CD90.1 and CD44, which are known liver cancer stem cell markers (LCSC)." (PMID 34626204, 2021). "Recent studies dealing with CD44 also revealed that HCV would replicate at higher rates in liver cancer stem cells than in differentiated hepatocytes, which is of utmost importance for the comprehension of HCV-induced liver disease, notably HCC." (PMID 34065048, 2021). "We firstly evaluated CD44 expression as a marker of CSCs in four liver cancer cell lines (HLE, HLF, Huh7, and HepG2)." (PMID 32585841, 2020). "In hepatic cancers, CD44 has been extensively used in combination with other putative surface markers to isolate CSCs from tumors." (PMID 32987767, 2020). "First, the expression levels of liver cancer-associated markers, AFP, GPC3 and CK19 as well as liver CSC markers, CD44, CD24 and CD133, in malignant tumours were relatively high compared to that in normal liver by RT-qPCR." (PMID 32203212, 2020). "We used CD133/CD44/CD24/EpCAM MicroBeads to isolate hLCSCs from human liver cancer cell line Huh7 by detecting the markers of hLCSCs, including CD133, CD44, CD24 and EpCAM." (PMID 29602239, 2018). "In this study, we isolated CD13+CD44+ sphere cells (SCs) derived from liver cancer tissues and SK-Hep-1 cells, which possessed cancer stem cell-like properties." (PMID 28199981, 2017). "We found that CD44 expression was associated with drug resistance, tumorigenicity and cellular metastasis and CVV can successfully eradicate metastatic liver cancer cells." (PMID 29069721, 2017). "The number of liver cancer progenitor cells (defined as CD44+/CD31− Ter119− CD45−) was significantly increased in RAF1-deficient organs." (PMID 28000790, 2016). "Analyses of human liver samples revealed that CD133+CD44+ liver cancer cells were related to metastasis to the liver portal vein." (PMID 27610139, 2016).
liver cancer (continued). "Using antibodies against CD44 and EpCAM1 (markers of mesenchymal stem cells and liver cancer progenitor cells) we identified cells expressing LPAR3 in the HCC-NTL margin also expressed these stem cell markers." (PMID 26701886, 2016). "This suggests that CD44 positively correlate with malignant degree of liver cancer and negatively correlate with stemness state of liver CSCs." (PMID 26540347, 2015). "Our data indicated nuclear CD44 in liver cancer stem cells is responsible for the poorly differentiated highly malignant tumor cells by maintenance of low stemness state." (PMID 26540347, 2015). "In liver CSCs model, we not only found CD44 function importantly, this protocol can provide a platform to study liver cancer stem cells in therapeutic tumor treatment and evaluation of treatment efficacy." (PMID 26540347, 2015). "Our study validated CD44 have vital function in liver cancer stem cells through maintaining poorly differentiated tumor cells population." (PMID 26540347, 2015). "To compare the growth and gene expression between liver cancer stem cell and unstemic liver cancer cells, we isolated the liver cancer stem cells from human liver cancer cell line Huh7 by CD133/CD44/CD24/EpCAM MicroBead according to the schematic digram." (PMID 26513297, 2015). "In accordance to our results, sorafenib is unable to induce apoptotic response on CD44+ cells in liver cancer." (PMID 26556861, 2015). "Some studies have reported that abnormal gene expression, such as that of CD151, CD44, CD44s, CK-19, MMP, OPN, KLF8, TGF-beta and HRP-3, is closely associated with the development and progression of liver cancer." (PMID 24324629, 2013). "Here, we report a change in the expression of a CD44 variant isoform (CD44v8-10) in an 8-year-old female LFS patient with osteosarcoma and atypical liver cancer after chemotherapy." (PMID 23031740, 2012). "In our model, liver cancer cells with a mesenchymal phenotype demonstrate TISCs characteristics, including tumor-sphere formation and increased expression of CD44 and Nanog." (PMID 21929801, 2011). "CD133 and CD44 serve as surface markers of liver cancer stem cells." (PMID 41425729, 2025). "By systematically optimizing the composition of the sterosome and the HA coating conditions, we sought to construct a nanocarrier that exhibits favorable physicochemical properties, enhanced biocompatibility, and selective uptake by CD44-overexpressing liver cancer cells." (PMID 40862923, 2025). "Reminiscent of human liver cancers that express both lineages, we noted the upregulated expression of stemness markers such as Sox9, Sox4, Cd44, Prom1 and Cd24a in HepYF-M13 and HepYF-M14 cells compared to their expression in normal hepatocytes and H2.35 immortalized hepatocytes." (PMID 39051113, 2024). "CD44 and integrins might represent a suitable target for interfering with metastatic spreading of liver cancer." (PMID 37174657, 2023). "CD44 upregulates expression of integrin β2 and promotes transendothelial migration of liver cancer cells, which may facilitate metastatic spreading." (PMID 37174657, 2023). "Overall, our results suggest that CD44 may be a promising target for intervening with metastatic spreading of liver cancer." (PMID 37174657, 2023). "In conclusion, this finding not only provides a new perspective for the preparation of high-performance nanomicelles based on oligomeric HA but also offers strong evidence for the treatment of liver cancer by CD44 targeting and pH-sensitive drug delivery strategies." (PMID 35261298, 2022). "Thus, we examined the role of FOXM1 in the establishment of the CSC characteristics and regorafenib resistance via CD44 using the HepG2 and Hep3B liver cancer cell lines." (PMID 35887129, 2022). "Along these lines, the goal of this study to assess the role of CD44 as a target receptor for drug distribution and the efficacy of HA-modified liposome uptake in liver cancer cells may have some clinical relevance." (PMID 35164326, 2022).
liver cancer (continued). "TIPRL/LC3/CD133/CD44 have also provided excellent potential for prognosticating patients with grade 1 iCCA and grade 1 HCCs, together with demonstrating that TIPRL/LC3/CD133/CD44 are, either individually or in conjunction, potential biomarkers for early liver cancer." (PMID 34208132, 2021). "Overall, this study reports that TIPRL/LC3/CD133/CD44 could, either individually or in conjunction, serve as potential biomarkers for early liver cancer." (PMID 34208132, 2021). "In addition, CD133+ subpopulations preferentially expressed CD44 in four hepatic cancer cell lines, including Huh7, MHCC-97L, MHCC-LM3, and SMMC-7721." (PMID 32987767, 2020). "To further confirm that the miPS-Huh7cmP1 cells were enriched with the cells expressing liver cancer-associated markers (AFP, GPC3 and CK19) and CSC markers (CD44, CD133 and CD24), we examined the gene expression levels compared to those in miPSCs and miPS-Huh7cm cells." (PMID 32203212, 2020). "β-Catenin and its downstream CD44 were known as canonical markers of liver cancer stem cells." (PMID 33363211, 2020). "CD133+ and CD44+ were proposed to be markers of tumor-initiating cells (TICs) in liver cancers." (PMID 30064482, 2018). "A recent study using liver cancer cell lines relates the close interaction between CD44 and CD166." (PMID 27465541, 2016). "Furthermore, compelling evidence suggests that CD44 is related to stemness in liver cancer." (PMID 38783892, 2024). "Surface markers, such as CD13, CD44, EpCAM, CD90, CD24, CD34, CD47, ICAM1, EpCAM, LGR5, and OV6, are widely recognized as markers of LCSCs, because of their association with proliferative capacity, self-renewal capacity, drug resistance, and recurrence of liver cancer." (PMID 38009775, 2023). "Moreover, flow cytometry analysis of stem cell surface markers commonly used for isolating liver cancer stem cells demonstrated that, while expression of CD44 and CD90 remained unchanged upon Dox treatment, EpCAM + cell population significantly increased in both Dox‐treated LCSCs and nonstem cells." (PMID 33524223, 2021). "Besides, celecoxib depleted CD44 + /CD133 + hepatic cancer stem cells (hCSC)." (PMID 24721996, 2014). "Osteosarcoma originates from mesenchymal tissue, not epithelial tissue, meaning that the CD44 variant isoforms expressed in osteosarcoma may have a completely different function from those expressed in liver cancer." (PMID 23031740, 2012). "proved the co-expression of cancer initiation cell (CIC) markers CD44 and CD133 with CD176 on lung, breast, and liver cancer." (PMID 37915564, 2023). "The results showed that these genes were highly expressed in liver cancer including CD80, CD44, HAVCR2, NRP1, and LAIR1." (PMID 35067176, 2022). "The present study showed that pinealectomy or exposure to constant light resulted in a significant increase in AFP, CD44, TGFβ-1, and VEGF levels indicating early development and progression of hepatic cancer cells." (PMID 35419691, 2022). "As demonstrated by their enhancement of tumorigenicity, the liver cancer stemness markers CD326, CD133, CD44, ALDH1A1 and CD13 were found mostly downregulated in ARID3A knockdown cells and upregulated in ARID3A overexpressed cells." (PMID 36008383, 2022). "CD44 regulates the expression of PES1 by regulating miR-105-5p and promotes the proliferation of liver cancer cells." (PMID 34712323, 2021). "Given the variables’ relationship with the OS of liver cancer patients, we further examined the roles of all five variables, TIPRL, LC3 (ATG7), CD133, CD44, and CD46, in normal liver (Chang), HCC (huh7), and iCCA (SNU1097) cell lines." (PMID 34208132, 2021). "We analyzed the composition of tissues from patients with liver cancer using immunofluorescence probes for FAP (a marker for fibrosis) and CD44 (a marker for cancer cells)." (PMID 32210281, 2020).
liver cancer (continued). "A number of surface markers for liver cancer stem cell (LCSC) subpopulations (EpCAM, CD133, CD44, CD13, CD90, OV-6, CD47, and side populations) in HCC have been identified." (PMID 32466488, 2020). "Immuno-reactive liver cancer markers AFP, GPC3 and CK19 were positively stained as well as the CSC markers such as CD44, CD24 and CD133 in the tumour tissue developed in the liver." (PMID 32203212, 2020). "The hepatocellular carcinoma phenotype is driven by liver cancer stem-like cell (LCSLC) subpopulations CD133+, CD90+, CD44+, CD13+, and CD24+, which are endowed with self-renewal." (PMID 33376561, 2020). "By targeting the markers cluster of differentiation (CD) 90, CD44, CD133 and epithelial cell adhesion molecule (EpCAM), it has proven possible to differentiate between liver cancer stem cells (LCSC) and liver cancer cells." (PMID 30326865, 2018). "Our results suggest that c-JUN activates CSCs-related genes in liver cancer stem cells, but more studies are needed to understand the network of MBD3, c-JUN, EMT and CD44." (PMID 27894081, 2017). "A number of markers, including CD13, CD44, CD24, CD90, CD133, EpCAM, DLK1, ALDH1 can be used to identify liver cancer stem cells." (PMID 28930164, 2017). "Hepatic cancer stem cells have been identified by several markers, including EpCAM, CD90, CD133, CD44, CD24, and CD13." (PMID 26556861, 2015). "Several different markers can be identified such as CD133, CD90, CD44, CD326 (EpCAM) or by selecting the side population (SP) cells by Hoechest dye-staining in order to isolate CSCs from liver cancers." (PMID 26097877, 2015). "Liver CSC markers include EpCAM, CD133, CD90, CD44, CD24, CD13, and OV6, some of these markers are considered functional with highly invasive, metastasis, chemotherapy resistant of liver cancer." (PMID 26540347, 2015). "In the isolated cells from human liver cancer cell line Huh7, Cells with CD133+/CD44+/CD24+/EpCAM+(HLCSC) was 15.3 ± 5.26%, Cells with CD133−/CD44−/CD24−/EpCAM-(non-HLCSC) was 5.23 ± 2.56% and others was 79.43 ± 5.19% (P < 0.01, respectively)." (PMID 26513297, 2015). "CD44, CD90, CD133, and EpCAM are the cell–surface markers of liver cancer stem cells, further, Oct-4 and BMI-1 are the key ‘stemness’ genes in CSCs from various cancers." (PMID 24806207, 2014). "More importantly, we were able to provide direct evidence by a sandwich ELISA that CD44 is indeed the carrier molecule for CD176/TF in lung, breast and liver cancer cells, confirming earlier data from colorectal carcinoma." (PMID 23888272, 2013). "Additional genes related to hepatic cancer stem cells were more expressed in MHN than in SHN, although their fold-changes were lower than 10 (CD133, THY-1, CD44)." (PMID 23185381, 2012). "In human liver cancer, CD45−/CD90+/CD44+ cells form metastatic lesions in the lungs of immune compromised mice, and blockage of CD44 activity by an antagonizing antibody is shown to block tumor growth and metastasis." (PMID 21347385, 2011). "Additionally, in sorafenib-treated liver cancer patients, TIPRL, LC3, and CD133, showed a substantial HR and 95% CI, except for CD44." (PMID 34208132, 2021). "For example, BANCR can be used as a potential therapeutic target for liver neoplasms, NEAT1 is necessary for liver neoplasm marker CD44 expression, and LINC00473 promotes the progression of liver cancer by acting as microRNA-195 ceRNA and increasing HMGA2 expression." (PMID 35058974, 2021). "We also confirmed that our sorted EpCAM−/CD133− or EpCAM+/CD133+ cell populations are not enriched for other common liver cancer stem cell markers CD44 or CD90." (PMID 33524223, 2021). "However, significant induction of hepatic cancer stem cell markers (MDR1, EPCAM, CD44 and CD133) in the tumors and surrounding liver tissue was attenuated upon GKT771 treatment." (PMID 33485364, 2021).